PINK1 (PTEN induced kinase 1)
Diseases named in the same sentence as PINK1 in open-access papers (continued):
Sharing a sentence is not in itself a finding about the gene and the disease.
tumor (157 papers, 2008 to 2026). "PINK1, a gene frequently linked to EPCs, has been recognized as a tumor suppressor in CRC by modulating cellular metabolism." (PMID 40842994, 2025). "Under stress conditions such as chemotherapy and radiotherapy, tumor cells can activate mitophagy through pathways such as PINK1/Parkin, BNIP3, or FUNDC1 to counteract the damage caused by drugs and radiation, leading to the development of resistance." (PMID 41551160, 2025). "Immunohistochemical staining reveals higher PINK1 expression in tumor tissues, which is strongly linked to the tumor-node-metastasis classification and is associated with longer overall survival in non-small cell lung cancer (NSCLC) patients." (PMID 39179991, 2024). "In glioblasts, PINK1 can negatively regulate the growth of tumour cells, and the loss of its expression can stabilize HIF1a and then induce the production of ROS and tumour growth." (PMID 36200262, 2022). "The increased expression of Beclin1, LC3II, PINK1/Parkin, and Drp1 directed the involvement of mitophagy in supporting the apoptosis induction of GC cells, which subsequently caused the breakdown of tumor-cell homeostasis and death." (PMID 36145507, 2022). "To study the mechanisms underlying PINK1-regualted tumor growth in vivo, we examined cell proliferation rates in tumor tissues derived from WT, PINK1-/- and PINK1-/-plus huPINK1 cells in nude mice." (PMID 35600352, 2022). "Overall, these results show that in human tumor cells with a common Ras mutation, the loss of PINK1 also causes impaired tumor growth." (PMID 35600352, 2022). "We also show that PINK1 deficiency impairs Drp1 phosphorylation in tumor cells, as has been reported previously in other cells." (PMID 35600352, 2022). "Another emerging role of PINK1 concerns tissue growth and tumorigenesis; it is known that PINK1 is downregulated in PTEN-mutated tumor cells." (PMID 34831247, 2021). "Deficiency of Pink1 and Park2 promotes pancreatic tumorigenesis in Kras-driven tumor model by increasing mitochondrial iron accumulation and AIM2/HMGB1 pathway-mediated PD-L1 expression." (PMID 34493296, 2021). "PINK1 encodes the protein PTEN induced kinase 1, a mitochondrial serine/threonine-protein kinase and a tumor suppressor." (PMID 32210791, 2020). "We further explored the correlation between PINK1 expression and representative immune markers in LIHC and LUSC, and PINK1 expression was more strongly correlated with tumor-associated macrophage markers such as HLA-G, CD80, and CD86 in LUSC than in LIHC." (PMID 33244455, 2020). "Later on, mounting evidence indicates that PINK1 is implicated in diverse aspects of tumor biology." (PMID 37940999, 2023). "Thus, the reduced growth of PINK1-deficient RasG12D-transformed cells in vitro is validated and supported by reduced proliferation of the corresponding tumor cells in nude mice." (PMID 35600352, 2022). "Here, we investigated whether loss of PTEN-induced kinase 1 (PINK1) - a mitochondrial kinase linked to recessive familial Parkinsonism - affects the growth of oncogenic Ras-induced tumor growth in vitro and in vivo." (PMID 35600352, 2022). "Inhibition of DRP1 diminished PINK1-regulated mitochondria morphological changes and tumor growth suggesting that PINK1 deficiency primarily inhibits Ras-driven tumor growth through disturbances in mitochondrial fission and associated cell necrosis and cell cycle defects." (PMID 35600352, 2022). "Taken together, these results suggest that aberrant mitochondrial dynamics due to impaired phosphorylation of Drp1 and associated cell cycle and cell survival defects may be primary mechanisms underlying reduced tumor cell growth in PINK1-/- MEF cells." (PMID 35600352, 2022). "In addition, PINK1 expression was more strongly correlated with tumor-associated macrophage markers, such as HLA-G, CD80, and CD86, in LUSC than in LIHC." (PMID 33244455, 2020).
tumor (continued). "In addition, several of the genes discovered to cause inherited PD, including PTEN induced putative kinase 1 (PINK1) have been described to have oncogenic or tumor suppressor properties." (PMID 26973853, 2016). "Silencing of TRAP1 in tumor cells also causes mitochondrial swelling, loss of ψm, rapid increase in intracellular ROS generation and release of cytochrome C, identical to the effects of PINK1 knockdown." (PMID 18560593, 2008). "Therefore, PINK1 loss inhibits tumor growth at least in part through impaired regulation of Drp1." (PMID 35600352, 2022). "While chronic inflammation may contribute to pathogenesis of PDs, in the setting of the immunosuppressive tumor microenvironment, Pink1/Prkn deficiency may be beneficial to enhance STING-mediated type I IFN production especially in the setting of mitochondrial stress such as radiation treatment." (PMID 33520994, 2020). "Targeted inhibition of MYOF activates tumor-suppressive mitophagy via the PINK1-Parkin axis, indicating MYOF as a potential therapeutic target in PTC." (PMID 42271528, 2026). "Acetate, on the other hand, supplements acetyl-CoA, partially counteracting the metabolic changes induced by PINK1 overexpression, thereby attenuating its tumor-suppressive effects." (PMID 41355959, 2026). "The differential expression of GPR55 and PINK1 in tumor versus normal tissues further supports their potential as biomarkers and therapeutic targets." (PMID 40565152, 2025). "The immunostaining pattern for PINK1 varied among tumor samples, showing weak to moderate or intense cytoplasmic positivity." (PMID 40243539, 2025). "Under the strong mitochondrial damage stimulation of chemotherapy, the overactivation of the PINK1/Parkin pathway can lead to fatal autophagic lysosome rupture, resulting in tumor cell death." (PMID 40761374, 2025). "In GBM and PAAD, PINK1 expression is notably downregulated in tumor samples, aligning with its reported epigenetic silencing in these malignancies." (PMID 40565152, 2025). "Ketoconazole and mitochondria-targeted metformin (Mito-Metformin) trigger mitophagy through regulation of the PINK1/Parkin pathway, leading to suppressed tumor cell proliferation." (PMID 41551160, 2025). "The comparison between normal and primary tumor tissue samples shows an extremely significant difference in PINK1 expression, with a p-value of 1.11 × 10−16." (PMID 40565152, 2025). "Studies have shown that key proteins involved in autophagy, such as PINK1, Parkin, BNIP3, and NIX, are important intermediates of various physiological processes in cells, and the genes encoding these proteins are tumor suppressor genes that promote apoptosis." (PMID 40837014, 2025). "Building upon these findings, we further investigated PINK1 expression by directly comparing its levels in tumor tissues from both primary and metastatic lesions, aiming to explore its potential applicability in routine pathological practice." (PMID 40243539, 2025). "We further detected the expression of mTOR, p-mTOR, PI3K, Akt, p-Akt, PINK1, and Parkin in tumor tissues via WB." (PMID 40944197, 2025). "For example, PINK1 and Parkin, key proteins in the ubiquitin-dependent mitophagy pathway, have been shown to be critical in tumor suppression." (PMID 41138746, 2025). "The role of PINK1 appears to be context-dependent, with findings indicating it can function either as an oncogene or as a tumor suppressor depending on cellular conditions." (PMID 41300754, 2025). "Both in vitro and in vivo experiments confirmed that DARS2 inhibited cellular senescence and facilitated tumor progression by enhancing PINK1-mediated mitophagy." (PMID 39990673, 2025). "PINK1 suppresses CRC progression by promoting mitophagy and reducing acetyl-CoA production; loss of PINK1 leads to elevated acetyl-CoA and enhanced tumor growth through epigenetic and metabolic shifts." (PMID 41359051, 2025).
tumor (continued). "Regarding radiotherapy, tumor hypoxia initiates pro-survival mitophagy, driving radioresistance, whereas blocking the PINK1/Parkin axis or administering mitochondrial-targeted antioxidants restores radiosensitivity." (PMID 40761374, 2025). "In tumor tissues, the tumor suppressor PTEN induces expression of PINK1, while PINK1, in turn, regulates the PI3K/AKT signaling pathway." (PMID 40860809, 2025). "Galactan RN0D, isolated from the TCM Sanqi, has been identified as an activator of the PINK1/Parkin pathway, ultimately activating cytotoxicity in tumor cells." (PMID 40134432, 2025). "Further experiments demonstrated that AC484 exerted anti‐tumor activities by TFRC‐mediated PINK1‐PRKN‐dependent mitophagy." (PMID 40734623, 2025). "DARS2 knockdown significantly reduced tumor size and weight, an effect partially reversed by PINK1 overexpression." (PMID 39990673, 2025). "HIF-1α mitigates oxidative stress through the HEY1/PINK1 pathway, and PINK1 expression can be modulated by changes in oxygen levels, impacting mitochondrial development in tumor cell lines." (PMID 39408813, 2024). "Inhibiting mitophagy has been noted to elevate chemosensitivity in tumor cells, reducing their ability to resist drug interventions, particularly through the action of PINK1." (PMID 38913914, 2024). "DRP1 induces mitochondrial fission while Parkin, a component of the PINK1/Parkin‐mediated pathway, functions as a tumor suppressor." (PMID 38334464, 2024). "LGALS3 and G6PD were highly expressed in the CHI, S2-S4, and tumor groups, and PINK1 was highly expressed in the normal, S0-S1 and paracancerous tissues." (PMID 37180150, 2023). "On the other hand, the loss of PINK1 and PRKN allows the cell cycle to proceed, meeting the metabolic demands of the tumor and promoting the progression of NSCLC." (PMID 38155968, 2023). "Cox univariate and multivariate analyses revealed that PINK1, PARK2, and tumor size were closely associated with the prognosis of patients with ESCC, and PARK2 was an independent risk factor for patients with ESCC." (PMID 37833780, 2023). "Fifth, immunohistochemical analysis was carried out using tissue microarrays; however, the PINK1 immunoexpression pattern was quite homogeneous and concordant in the three representative tissue cores selected from each tumor." (PMID 37047483, 2023). "Diverse subcellular PINK1 are involved in different signaling cascades to regulate tumor occurrence and development." (PMID 37940999, 2023). "Our study has shown that PINK1 promoted tumor metastasis and drug resistance dependent on its kinase activity." (PMID 37940999, 2023). "In xenograft models, we found that PINK1 inhibition can improve the chemotherapy effect of cisplatin and reduce the ability of tumor metastasis." (PMID 37940999, 2023). "PINK1 induces mitochondrial dysfunction, oxidative stress, and cell death and promotes tumor growth." (PMID 37833780, 2023). "Similar findings in vivo also supported this concept, showing that GPD1L suppressed tumour growth by promoting PINK1‐mediated mitophagy." (PMID 37382962, 2023). "Further investigations of the role of Atad3a-Pink1-mitophagy axis in regulating in vivo antitumor immunity showed that simultaneous knockdown of Pink1 reversed the effect of Atad3a knockdown on tumor growth." (PMID 36627348, 2023). "On the other hand, they activate PINK1/Parkin-regulated mitophagy, which hinders mitochondria-induced tumor-killing activity." (PMID 35370635, 2022). "Using the caspase 3/7 apoptosis detection kit, we also observed increased apoptosis of PINK1-/- tumor cells in nude mice." (PMID 35600352, 2022). "Compared with the control groups, PINK1 knockdown or sorafenib treatment alone significantly delayed tumor growth." (PMID 35370635, 2022).
tumor (continued). "PINK1 is under expressed in GBM while GBM tumor growth and the Warburg effect have been shown to be partially dependent on PINK1 expression." (PMID 36552827, 2022). "On the other hand, because PINK1 is upregulated in many tumor cells, can inhibition of its kinase activity suppress abnormal cell proliferation to treat tumorigenesis?" (PMID 35874823, 2022). "The tumor formation of PINK1-/- cells was significantly reduced when compared with PINK1+/+ cells in nude mice." (PMID 35600352, 2022). "Through the pilot study on the antitumor mechanism, we found that TPP-SS-ATS-LS inhibit tumor cell proliferation through PINK1 dependent mitophagy, which was mediated by down-regulating the expression of PHB2." (PMID 35964052, 2022). "Analysis of the expression of Drp1 and phosphorylated Drp1(Ser616) showed that phosphorylation of DRP1 was also decreased in PINK1-/- tumor tissues." (PMID 35600352, 2022). "Intriguingly, in CRC, SIRT3 displays an oncogenic role by deacetylating SHMT2, and acts as tumor suppressor by increasing ROS production and PINK1/Parkin/mitophagy axis activation." (PMID 34680344, 2021). "Recent studies have reported the role and mechanism of PINK1 in tumor proliferation, metastasis, apoptosis and tumor resistance." (PMID 33981484, 2021). "The regulation of mitophagy, via mechanisms other than PINK1/Parkin, can inhibit the migration of tumor cells." (PMID 34589426, 2021). "The impaired PINK1-PRKN-dependent mitophagy pathway also promotes various types of tumor formation, including PDAC (discussed later)." (PMID 33718171, 2021). "Low oxygen environments can alter PINK1 expression, reducing mitobiogenesis in tumor cell lines indicating PINK1 expression can be altered as an adaption to change of oxygen levels." (PMID 34439955, 2021). "In conclusion, we confirmed that NFIB can promote the proliferation and metastasis of tumor cells by transcriptionally regulating the expression of PINK1 in KIRC." (PMID 33981484, 2021). "Taken together, these results suggested that PINK1 is a critical target of NFIB and that PINK1 exerts tumor-promoting roles in KIRC." (PMID 33981484, 2021). "BRCA1 is a well-studied tumor suppressor involved in the homologous repair of DNA damage, whereas PINK1, a mitochondrial serine/threonine kinase, is known to be involved in mitochondrial quality control." (PMID 33888730, 2021). "The thyroid hormone T3 mediates ubiquitination of mitochondrial HBX in HBV-infected cells through PINK1 to simultaneously promote mitophagy and mitochondrial biogenesis, inhibit the production of mitochondrial ROS, and reduce the tumor-promoting effect of HBV." (PMID 34589426, 2021). "TBK1 constitutively interacts with OPTN to act as a key modulator to initiate elimination of damaged mitochondria via selective mitophagy (PINK1/Parkin-dependent mitophagy), that is involved in tumor suppression pathways." (PMID 32514015, 2020). "Mice injected with PINK1 overexpressing MM cells had significantly less tumor burden and bone destruction, compared to mice injected with MM cells transduced with control vector." (PMID 32154065, 2020). "A low PINK1 mRNA expression was significantly related to higher tumor stage and positive nodal status." (PMID 33139776, 2020). "Many studies reported that mitophagy-associated molecules PINK1, Parkin, BNIP3, FUNDC1 promote tumor development, and provide targets for therapeutic inhibition in multiple cancers." (PMID 32587855, 2020). "In line with our expression studies, knockdown of HEY1 repressed tumor growth whereas knockdown of PINK1 augmented tumor growth in vivo." (PMID 31819034, 2019). "The present study demonstrated that in C26 tumor bearers the mitophagy marker PINK1 increased, whereas the other mitophagy-related protein BNIP3 was not significantly affected, although it showed an increasing trend." (PMID 30823492, 2019). "The exogenous expression of PTEN (Phosphatase and Tensin Homolog), a primary tumor suppressor, upregulates PINK1." (PMID 30274236, 2018).
tumor (continued). "The reduction of PINK1 activity limits the proliferation of tumor cells by inhibiting the cell cycle just before cell division." (PMID 30344951, 2018). "The knockout mice for PINK1 present significant defects in cell cycle progression, this indicates that PINK1 has tumor-promoting properties." (PMID 30274236, 2018). "In ROS-driven processes, PARKIN translocates to mitochondria of primary neurons; by contrast, it translocates to the uncoupled mitochondria of tumor cell lines, and it participates in the clearance of damaged mitochondria under PINK1’s influence." (PMID 30274236, 2018). "Third, therapeutic drug induced mitochondrial damage can lead to the activation of PINK1-induced mitophagy in cells and a tumor-bearing animal model." (PMID 29416672, 2018). "Of the 78 available sequenced tumor samples, we found increases in the mutation frequency of all 3 of these genes: BUB1B increased from 2 to 7% of patients, PINK1 from 1 to 7% of patients, and COL16A1 from 4 to 11% of patients." (PMID 28173755, 2017). "An additional 4-month exposure to the BRAF inhibitor vemurafenib resulted in a highly drug resistant tumor that showed 3 additional new DNA mutations in the genes BUB1B, PINK1, and COL16A1." (PMID 28173755, 2017). "A number of somatic mutations in two other genes unequivocally linked to PD, namely PINK1 and LRRK2, both of which encode protein kinases, were identified in tissue samples from patients with various tumours." (PMID 21203498, 2010). "Furthermore, although acetate promotes tumor cell apoptosis in CRC 40,41, it reverses the anticancer effects of PINK1 overexpression in a mouse model, leading to tumor growth restoration." (PMID 41355959, 2026). "At higher concentrations, autophagy and lysosome biogenesis genes, such as SQSTM1/p62, LAMP2, and PINK1, were robustly upregulated along with tumor suppressors, such as PTEN, and pro-apoptotic factors, including BAD and BIK, which reinforce autophagic flux and promote cellular homeostasis." (PMID 40671124, 2025). "Mechanistically, UNC13B may exert tumor-promoting effects by modulating key regulatory proteins, including PINK1, CDK2, AKR7A3, and Bim." (PMID 41007649, 2025). "A low level of PINK1 expression induces ROS formation and tumor brain growth." (PMID 40943612, 2025). "Depending on the context, PINK1 can function as either a tumor promoter or suppressor." (PMID 39859167, 2025). "This anti‐tumor effect was mediated through the inhibition of the Notch signaling pathway, leading to downregulation of key mitophagy‐associated proteins, including LC3, PINK1, and Parkin." (PMID 40830080, 2025). "PINK1 functions as a tumor promoter or suppressor, depending on the context." (PMID 39859167, 2025). "Overexpression of SIRT1 enhanced FOXO3 deacetylation and activity, promoting BNIP3 transcription and PINK1/Parkin-mediated mitophagy, which in turn promoted cell proliferation, migration, invasion, and inhibited apoptosis in vitro, as well as increased tumor growth and hormone resistance in vivo." (PMID 39266959, 2024). "Specifically, we delineate the erythrocyte (RBC) membrane-camouflaged EcN, termed as Trojan horse EcN@RBC, which triggers apoptosis in tumor cells by mitigating mitochondrial membrane potential (MMP) and subsequently activating the PINK1/Parkin pathway associated with mitophagy." (PMID 39415764, 2024). "Studies shown that PINK1 knockdown leads to mitochondrial dysfunction, increased ROS generation, and decreased mitochondrial membrane potential, which culminates in suppressed autophagy and affects tumor cell proliferation and migration." (PMID 39179991, 2024). "Notably, we observed a significant reduction of PINK1 immunofluorescence in tumor tissues of PANC-1 and MIA PaCa-2 xenografts treated with AP-4-139B." (PMID 38802657, 2024). "Moreover, western blot revealed that the gavage of SI significantly down-regulated P62, and up-regulated LC3 II/I, PINK1, and parkin in tumor xenografts (P < 0.01)." (PMID 38191316, 2024).